TMEM200A (transmembrane protein 200A)
Synonyms: KIAA1913; TTMC; TTMA
Tractability: Antibody: UniProt predicts a signal peptide or a membrane-spanning region. PROTAC: its protein half-life has been measured.
Gene: Protein-coding gene on chromosome 6 (130,365,404 to 130,443,424, forward strand). Ensembl gene ENSG00000164484.
Subcellular location: Membrane
Gene Ontology:
Molecular function: protein binding
Cellular component: membrane
Genetic constraint (gnomAD): Loss-of-function variants: 12 observed, 25.45 expected, observed/expected ratio (o/e) 0.47, 90% interval 0.3 to 0.76. The upper end of that interval is the gene's LOEUF score, 0.76, which puts it in group 3 of 6, group 1 being the genes least tolerant of losing a copy. Missense variants: 545 observed, 646.15 expected, observed/expected ratio (o/e) 0.84, 90% interval 0.79 to 0.9. Synonymous variants: 224 observed, 236.96 expected, observed/expected ratio (o/e) 0.95, 90% interval 0.85 to 1.06.
Homologues: Orthologues: chimpanzee TMEM200A (99% identical), macaque TMEM200A (98% identical), rabbit TMEM200A (93% identical), pig TMEM200A (93% identical), mouse Tmem200a (91% identical), dog TMEM200A (90% identical), rat Tmem200a (90% identical), tropical clawed frog tmem200a (72% identical), zebrafish tmem200a (64% identical), Drosophila melanogaster CG12502 (18% identical), Caenorhabditis elegans R05D7.3 (14% identical). Paralogues in human: TMEM200C (28% identical), TMEM200B (16% identical).
Diseases named in the same sentence as TMEM200A in open-access papers:
TMEM200A is named in the same sentence as 28 diseases in open-access papers, as found by Europe PMC text mining. Sharing a sentence is not in itself a finding about the gene and the disease. The quoted sentences say what the papers report.
gastric cancer (3 papers, 2023 to 2025). A primary or metastatic malignant neoplasm involving the stomach. "The 2 SNPs discarded by the Midrange Filter are located within genes associated with phenotypes unrelated to the mental health diagnoses of the PsyCourse participants: KCNH1 is associated with epilepsy and severe and rare development disorders, while TMEM200A is associated with gastric cancer." (PMID 40053832, 2025).
acute myeloid leukemia (2 papers, 2023). Acute myeloid leukemia (AML) is a group of neoplasms arising from precursor cells committed to the myeloid cell-line differentiation. "Bioinformatics analysis based on the Cancer Genome Atlas (TCGA) and Gene Expression Omnibus (GEO) databases showed that TMEM200A could be used to construct a risk score for the prognosis of acute myeloid leukemia (AML) and could effectively predict the OS of patients with AML." (PMID 36741965, 2023). "In previous studies, researchers have demonstrated that TMEM200A is involved in the progression of pancreatic cancer (Tan, Schaffalitzky de Muckadell & Joergensen, 2020) and acute myeloid leukemia (AML)." (PMID 37404478, 2023).
coronary atherosclerosis (1 paper, 2022). Atherosclerosis of the coronary vasculature. "In addition to MFGE8, we identified three additional previously unreported loci to be associated with coronary atherosclerosis, TMEM200A, PRG3 and FHL1 being the nearest genes of the lead variants." (PMID 35978133, 2022).
glioma (1 paper, 2020). A benign or malignant brain and spinal cord tumor that arises from glial cells (astrocytes, oligodendrocytes, ependymal cells). "The other well-predicted genes, including COL5A1, CPA4, CSTB, and PPIC in gliomas and DAK, ITPRIP, TM4SF19, TMEM200A in RCC have not been studied thoroughly in cancer and their roles in cancer worth further investigating." (PMID 32194984, 2020).
cancer (3 papers, 2020 to 2023). A tumor composed of atypical neoplastic, often pleomorphic cells that invade other tissues. "Finally, we explore the relationship between TMEM200A expression and cancer immune infiltrates using CIBERSORT." (PMID 37404478, 2023).
tumor (2 papers, 2023). "In contrast, TMEM200A had a positive connection with infiltration level of eosinophils, where, tumor-associated tissue eosinophils appear to be a good prognostic factor in gastrointestinal (Reichman, Karo-Atar & Munitz, 2016)." (PMID 37404478, 2023). "Co-expressed genes and GSEA indicated that TMEM200A may be an adhesion molecule closely associated with tumor invasion and metastasis." (PMID 36741965, 2023). "Moreover, we evaluated the association of TMEM200A with tumor-infiltrating immune cells." (PMID 37404478, 2023). "We also explored the correlation between TMEM200A expression and immune checkpoint expression to further understand the impact of TMEM200A on the tumor microenvironment (TME)." (PMID 36741965, 2023). "As a result, the expression level of TMEM200A was significantly different in group classified according to tumor T stage." (PMID 37404478, 2023). "We discovered that the expression of TMEM200A in GC tissues was significantly higher than that in adjacent non-tumor tissues (P = 1.382e−05)." (PMID 37404478, 2023). "GSEA identified five immune-related signaling pathways and five tumor-related signaling pathways significantly enriched in the high TMEM200A expression phenotype pathway." (PMID 37404478, 2023). "TMEM200A was up-regulated in GC tissues than that in adjacent non-tumor tissues based on TCGA database." (PMID 37404478, 2023). "Nevertheless, the reporting of TMEM200A was extremely inadequate, which hampers the assessment of its role in tumor progression." (PMID 37404478, 2023). "In addition, the possible biological functions and signaling pathways involved in TMEM200A and the relationship between TMEM200A expression and tumor-infiltrating immune cells were also analyzed." (PMID 37404478, 2023). "This is similar to the results of the co-expression gene enrichment analysis of TMEM200A, suggesting that TMEM200A may be an important adhesion molecule in extracellular information traffic and may be relevant to tumor immunity." (PMID 36741965, 2023). "In addition, the relationship between TMEM200A expression and tumor-infiltrating immune cells were also analyzed." (PMID 37404478, 2023). "Thus, the relationships between gene markers of immune cells and TMEM200A expression implicate the significant meaning of TMEM200A in regulating tumor immune microenvironment of GC." (PMID 37404478, 2023). "In addition, TMEM200A may upregulate immune checkpoints to help GC cells evade anti-tumor immune responses." (PMID 36741965, 2023). "We used the Tumor Immune Estimation Resource (TIMER) database and the ssGSEA algorithm to estimate the relationship between TMEM200A and immune cell infiltration." (PMID 36741965, 2023). "As a result, the expression level of TMEM200A was significantly different in group classified according to tumor T stage (P = 0.007), while not in tumor differentiation and pathological stage groups." (PMID 37404478, 2023). "In clinical samples, the expression level of TMEM200A was higher in tumor tissues compared with in adjacent non-tumor tissues (P = 0.018)." (PMID 37404478, 2023).
TMEM200A also shares sentences with these, for which no sentence is quoted: angina pectoris (1 paper); bone cancer (1); cardiomyopathy (1); cervical squamous cell carcinoma (1); cholangiocarcinoma (1); colon adenocarcinoma (1); endocervical adenocarcinoma (1); epilepsy (1); esophageal carcinoma (1); ischemic heart disease (1); kidney chromophobe (1); lung squamous cell carcinoma (1); metabolic disease (1); ovarian serous cystadenocarcinoma (1); pancreatic adenocarcinoma (1); pancreatic cancer (1); rectum adenocarcinoma (1); skin cutaneous melanoma (1); stomach adenocarcinoma (1); thymoma (1); uterine carcinosarcoma (1); uterine corpus endometrial carcinoma (1).